SAYSD1 (SAYSVFN motif domain containing 1)
Description:
Ufmylation 'reader' component of a translocation-associated quality control pathway, a mechanism that takes place when a ribosome has stalled during translation, and which is required to degrade clogged substrates. Specifically recognizes and binds ufmylated ribosomes when a ribosome has stalled, promoting the transport of stalled nascent chain via the TRAPP complex to lysosomes for degradation.
Synonyms: C6orf64; FLJ11101
Tractability: PROTAC: ubiquitination databases record sites on it; its protein half-life has been measured.
Gene: Protein-coding gene on chromosome 6 (39,104,063 to 39,115,193, reverse strand). Ensembl gene ENSG00000112167.
Subcellular location: Endoplasmic reticulum membrane; Cytoplasmic vesicle membrane
Subcellular location (Human Protein Atlas): Vesicles
Gene Ontology:
Molecular function: UFM1-modified protein reader activity
Biological process: protein quality control for misfolded or incompletely synthesized proteins; rescue of stalled ribosome
Cellular component: endoplasmic reticulum; endoplasmic reticulum membrane; cytoplasmic vesicle membrane
Genetic constraint (gnomAD): Loss-of-function variants: 19 observed, 16.96 expected, observed/expected ratio (o/e) 1.12, 90% interval 0.78 to 1.63. The upper end of that interval is the gene's LOEUF score, 1.63, which puts it in group 6 of 6, group 1 being the genes least tolerant of losing a copy. Missense variants: 247 observed, 241.35 expected, observed/expected ratio (o/e) 1.02, 90% interval 0.92 to 1.14. Synonymous variants: 105 observed, 108.56 expected, observed/expected ratio (o/e) 0.97, 90% interval 0.82 to 1.14.
Homologues: Orthologues: chimpanzee SAYSD1 (99% identical), dog SAYSD1 (85% identical), guinea pig SAYSD1 (77% identical), mouse Saysd1 (77% identical), pig SAYSD1 (75% identical), rat Saysd1 (75% identical), rabbit SAYSD1 (71% identical), macaque SAYSD1 (67% identical), tropical clawed frog SAYSD1 (51% identical), zebrafish saysd1 (38% identical), Caenorhabditis elegans C13F10.5 (25% identical), Drosophila melanogaster Saysd1 (25% identical).
Diseases named in the same sentence as SAYSD1 in open-access papers:
SAYSD1 is named in the same sentence as 4 diseases in open-access papers, as found by Europe PMC text mining. Sharing a sentence is not in itself a finding about the gene and the disease. The quoted sentences say what the papers report.
prostate carcinoma (1 paper, 2021). A carcinoma that arises from epithelial cells of the prostate gland. "Likewise, the lnc-SAYSD1-1 also bioinformatically allows to distinguish the ERG-positive from all the other subclasses of prostate cancer with a Gleason score ≤ 3+4." (PMID 33672425, 2021).
tumor (2 papers, 2017 to 2021). "This would explain an overexpression of lnc-SAYSD1-1 in an early stage of the tumor, such as that represented by Gleason ≤ 3+4, while the absence in subjects suffering from cancer with Gleason ≥ 4+3 could be understood as a positive prognostic factor." (PMID 33672425, 2021).
SAYSD1 also shares sentences with these, for which no sentence is quoted: cancer (1 paper); lung carcinoma (1).